FZD7 (frizzled class receptor 7)
Diseases named in the same sentence as FZD7 in open-access papers (continued):
Sharing a sentence is not in itself a finding about the gene and the disease.
triple-negative breast carcinoma (12 papers, 2016 to 2025). An invasive breast carcinoma which is negative for expression of estrogen receptor (ER), progesterone receptor (PR), and human epidermal growth factor receptor 2 (HER2). "Previously, we and others found FZD7 expression to be elevated in triple-negative breast cancer (TNBC) compared to other subtypes, making it a promising therapeutic target." (PMID 41218118, 2025). "According to bioinformatics analysis, FZD7 plays a significant role in the occurrence and development of triple-negative breast cancer (TNBC), suggesting that it is a good therapeutic target." (PMID 36276155, 2022). "FZD7 is overexpressed in triple negative breast cancer and interference with FZD7 signaling in this context reduces the EMT induced by WNT/β-catenin signaling." (PMID 34604862, 2021). "In triple negative breast cancer, FZD7 shRNA reduces cell proliferation and colony formation." (PMID 26716419, 2016). "In triple-negative breast cancer (TNBC), overexpression of MIR4435-2HG promotes frizzled homolog 7 (FZD7) expression in cells, thereby activating the Wnt/β-catenin signaling pathway." (PMID 35784328, 2022).
pancreatic cancer (9 papers, 2008 to 2025). "High level of FZD7 expression in pancreatic cancer samples was associated with earlier hepatic metastasis." (PMID 35854234, 2022). "Mining databases and data obtained from assays on human specimens had shown that Fzd7 is closely associated with Wnt7b, that Fzd7/Wnt7b expression is upregulated in pancreatic cancer tissues compared with normal tissues, and its expression is negatively correlated with survival." (PMID 33934523, 2021). "Therefore, we assume that FZD7 plays a role through the canonical WNT pathway, and that the TGF-β/SMAD3 pathway could be associated with the regulation of the FZD7/β-catenin pathway in the malignant biological behavior of pancreatic cancer cells." (PMID 35854234, 2022). "Objective of this study is to demonstrate that high FZD7 expression in pancreatic cancer can accelerate hepatic metastases and elucidate the related molecular mechanisms." (PMID 35854234, 2022). "Most datasets from the ONCOMINE database suggested that FZD7 expression was significantly higher in pancreatic cancer than in normal pancreatic tissue." (PMID 35854234, 2022). "Most datasets suggested that Fzd7 expression was significantly higher in pancreatic cancer compared with normal pancreatic tissue." (PMID 33934523, 2021). "As receptors and ligands, Fzd7 and Wnt7b were co‐expressed in the immunohistochemical staining of pancreatic cancer tissues to different degrees." (PMID 33934523, 2021). "Protein expression of Fzd7/Wnt7b in pancreatic cancer tissues is a prerequisite for further biological functional studies." (PMID 33934523, 2021). "FZD7/WNT7b signaling have been identified as contributors to chemoresistance in pancreatic cancer.These genes were both elevated in Panc320 following treatment with ETC-159 and paclitaxel and may explain the persistent growth rate." (PMID 38598488, 2024). "Similarly, in pancreatic cancer, elevated expression of Frizzled-7 (FZD7) derives the CSC phenotype and liver metastasis through the canonical Wnt/β-Catenin pathway." (PMID 39456967, 2024). "FZD7 is a Wnt co-receptor, and its expression in various cancers is associated with aberrant activation of the Wnt pathway promoting EMT, and thus metastatic development in prostate and pancreatic cancers." (PMID 37576552, 2023). "Based on the data from CCLE, we analyzed the correlation between the expression of Fzd7 and different Wnt proteins in various pancreatic cancer cell lines, and found that Wnt7b was more significantly associated with Fzd7 compared with other Wnt proteins relatively." (PMID 33934523, 2021). "Fzd7/Wnt7b is an important regulator of the stemness and drug resistance of pancreatic cancer cells, which may be due to PCSC subset regulation." (PMID 33934523, 2021). "Therefore, we hypothesized that Wnt7b was an important ligand which exhibited synergistic action with Fzd7 in living pancreatic cancer cells." (PMID 33934523, 2021). "Therefore, the levels of Fzd7/Wnt7b may be an important factor that can regulate the proportion of CSC subsets in pancreatic cancer cells." (PMID 33934523, 2021). "Therefore, FZD7 may play an important role in the EMT process of pancreatic cancer." (PMID 35854234, 2022). "It is currently believed that CSCs are more resistant to chemotherapy than normal tumor cells; Our previous study also showed that FZD7 can synergize with Wnt7b to increase the proportion of PDAC CSCs and enhance drug resistance of pancreatic cancer cells." (PMID 35854234, 2022). "High FZD7 expression in pancreatic cancer can accelerates hepatic metastases by promoting EMT and strengthening cell stemness, and FZD7 can work through the canonical Wingless-type (WNT) signaling pathway and participate in TGF-β/SMAD3 signaling pathway also." (PMID 35854234, 2022). "Correlation analysis between Fzd7 and Wnt7b in the R2 database and CCLE was performed, and the results showed that there was significant positive correlation between the expression of the two proteins in pancreatic tumors." (PMID 33934523, 2021).
lung carcinoma (7 papers, 2011 to 2022). "Moreover, FZD7 has been implicated in other types of cancers, such as breast and lung cancers, causing fibrosis." (PMID 35334792, 2022). "Since FZD7 is a transmembrane receptor in the WNT pathway, we further investigated whether MITF regulated cell invasion through FZD7 in lung cancer cells." (PMID 33293474, 2020).
prostate carcinoma (7 papers, 2015 to 2025). A carcinoma that arises from epithelial cells of the prostate gland. "FZD7, FZD8, and ROR2 showed the lowest expression in most of the prostate cancer cell lines, while FZD6 and RYK were abundantly expressed." (PMID 29930766, 2018).
cervical cancer (6 papers, 2016 to 2022). A primary or metastatic malignant neoplasm involving the cervix. "MicroRNA-142-3p inhibits cell proliferation and invasion of cervical cancer cells by targeting Frizzled class receptor 7 (FZD7)." (PMID 31168355, 2019). "In addition, knockdown of FZD7 expression in cervical cancer cells also lead to attenuated metastasis and invasion abilities, and FZD7 triggered by Wnt3α promotes renal cells proliferation and tumorigenesis." (PMID 29108281, 2017). "Down-regulation of FZD7 in cervical cancer cells could inhibit cell invasion and migration by inhibiting the expression level and activities of MMP2 and MMP9, as well as inhibiting the expression of phosphorylated JNK and c-jun." (PMID 29029485, 2017). "Moreover, subsequent studies from the same lab demonstrated FZD7 to be a direct target of miRNA-142-3p, which is normally expressed at low levels in cervical cancer cells." (PMID 27196929, 2016). "Importantly, restoration of miRNA-142-3p expression significantly reduced FZD7 expression, cell proliferation and invasion, thus identifying miRNA-142-3p and FZD7 as attractive therapeutic targets for cervical cancer therapy." (PMID 27196929, 2016). "There is no data to demonstrate that FZD7 is upregulated in cervical cancer, however the role of FZD7 in cancer could be underestimated, as seems the case in cervical cancer, due to changes in the membrane turnover of FZD7, which will greatly affect the response of a cell to Wnt ligands." (PMID 27196929, 2016). "Inhibition of FZD7 using shRNA was able substantially reduce invasion and EMT in HeLa and SiHa cervical cancer cell lines in vitro." (PMID 27196929, 2016). "Levels of phosphorylated c-Jun and JNK were also reduced when FZD7 was inhibited suggesting the PCP pathway maybe involved in transducing signals downstream of FZD7 in cervical cancer, although no assays were performed to determine the activation of canonical Wnt signalling." (PMID 27196929, 2016).
gastric tumors (6 papers, 2015 to 2025). "Indeed, in other gastrointestinal tumors it has been recently shown that inhibition of Wnt receptors (Fzd7) can block the initiation and growth of gastric tumors even in the presence of Apc mutations." (PMID 33372038, 2021). "Conditional deletion of c-Myc in Cre+;Apcfl/fl;Mycfl/fl mice showed a dramatic reduction of gastric adenoma initiation and Wnt activation compared to the respective controls, identifying c-Myc as a key modulator of gastric tumor growth downstream of Fzd7." (PMID 32486243, 2020). "Of the 10 Fzd receptors, Fzd2, 5, 7, 8, and 9 have been shown to be upregulated in GC tissue, with recent evidence from our group that Fzd7 is important in transmitting Wnt signaling in gastric tumors to drive tumor initiation and growth." (PMID 32486243, 2020). "FZD7, in turn, is the predominant Wnt receptor responsible for transmitting Wnt signaling in gastric tumor cells and plays an essential role in tumorigenesis." (PMID 31827644, 2019). "Recently, it was shown that FZD7 is the predominant Wnt receptor responsible for transmitting Wnt signaling in gastric tumor cells and plays an essential role in tumorigenesis." (PMID 31827644, 2019). "More selective antibodies and other therapeutics, such as those targeting FZD7, are being developed to inhibit canonical Wnt signaling specifically in cancers like colorectal and gastric tumors, where FZD7 overexpression drives tumor growth and resistance to apoptosis." (PMID 40376615, 2025). "Furthermore, the Wnt receptor Fzd7, which can bind Wnt3, transmits oncogenic Wnt signalling to drive the proliferation of gastric tumours in vivo." (PMID 36040316, 2022).
esophageal cancer (5 papers, 2014 to 2025). A primary or metastatic malignant neoplasm involving the esophagus. "FZD7 may serve as a novel prognostic marker and a potential therapeutic target for esophageal cancer patients." (PMID 29029485, 2017).
liver cancer (5 papers, 2015 to 2024). An epithelial or non-epithelial malignant neoplasm that arises from the liver. "We also demonstrated Fzd7 and GLUL are induced by p22 in vivo; this shows that genes associate with liver cancer (Fzd7) and β-catenin-mediated liver zonation and regeneration (GLUL,) are induced by p22 in normal hepatocytes." (PMID 32486480, 2020). "The study also demonstrated that Frizzled-7 (Fzd7) and Glutamate-Ammonia Ligase (GLUL), which have a known association with liver cancer and interact with TCF/β-catenin, are induced by p22 in vivo." (PMID 37112837, 2023).
endometriosis (4 papers, 2019 to 2023). The growth of functional endometrial tissue in anatomic sites outside the uterine body. "The relationship between the expression of FZD7 and clinicopathological characteristics of endometriosis patients." (PMID 37800830, 2023). "In order to examine the role of miR‐488 in mice with endometriosis, we measured miR‐488 expression and expression levels of Frizzled‐7 (FZD7), cyclinD1, β‐catenin, and c‐Myc in vivo and in vitro." (PMID 30729701, 2019). "In summary, we clarified that the expression of FZD7 was higher in ectopic endometrium than in eutopic endometrium and may be a potential therapeutic target for the prognostic marker for endometriosis still need further study." (PMID 37800830, 2023). "In this study, we aimed to investigate whether Frizzled-7 (FZD7) would effectively promote the development of endometriosis." (PMID 37800830, 2023). "The roles of C7, CFH, and FZD7 in endometriosis have been reported previously." (PMID 36339397, 2022). "In this study, we observed that miR‐488 expression was decreased while FZD7 was increased in artificial ectopic endometrial tissue when compared with normal endometrial tissue, which indicated miR‐488 and FZD7 had important roles in the endometriosis initiation and progression." (PMID 30729701, 2019). "However, the exact function of FZD7 in human endometriosis was unclear; thus FZD7 gene became a candidate gene that we were interested in." (PMID 30729701, 2019). "The positive expression of FZD7 protein in endometrial tissue of normal mice was 14.25%, while that of mice with endometriosis was 40.87%, suggesting a significant increase of the expression of FZD7 in ectopic endometrial tissue of mice with endometriosis (P < 0.05)." (PMID 30729701, 2019). "We aimed to predict the function and clinical significance of FZD7 in endometriosis." (PMID 30729701, 2019). "FZD7 may serve as a potential therapeutic target for endometriosis treatment." (PMID 37800830, 2023). "Then, we collected human endometrial and endometriotic tissues from patients with endometriosis of the ovary (n = 39) and control patients without endometriosis (n = 10, who underwent hysterectomy for uterine fibroids) to compare the expression of FZD7." (PMID 37800830, 2023).
esophageal squamous cell carcinoma (4 papers, 2017 to 2021). Esophageal squamous cell carcinoma (ESCC) is a type of esophageal carcinoma (EC) that can affect any part of the esophagus, but is usually located in the upper or middle third. "In esophageal squamous cell carcinoma, overexpression of FZD7 in the presence of WNT3a leads to an increase in downstream EMT target MMP7; the depletion of FZD7 inhibited EMT." (PMID 34604862, 2021). "FZD7 promoted cell growth, mobility, chemoresistance, metastasis and EMT in esophageal squamous cell carcinoma (ESCC)." (PMID 29789460, 2018).
tongue squamous cell carcinoma (4 papers, 2019 to 2025). A squamous cell carcinoma that arises from the tongue. "For example, in tongue squamous cell carcinoma, Sox8 can combine with the FZD7 promoter region of the Wnt receptor and activate the Wnt/β-catenin signaling pathway regulated by FZD7, thus regulating tumor cell chemosensitivity, stem cell stemness and EMT." (PMID 30670025, 2019). "SOX8 is over-expressed in tongue squamous cell carcinoma (TSCC), where it binds to the promoter region of FZD7 (frizzled class receptor 7), hyper-regulating its expression." (PMID 40568269, 2025).
Wilms tumor (4 papers, 2014 to 2025). An embryonal neoplasm characterized by the presence of epithelial, mesenchymal, and blastema components. "Another study displayed that an anti-FZD7 antibody was able to induce cell death and deplete stem cell properties in FZD7-positve Wilms’ tumor, and reduce in vivo cell proliferation and survival in mouse xenograft model." (PMID 29789460, 2018).
gastric adenoma (3 papers, 2020 to 2024). A neoplastic polyp that arises from the stomach. "Fz7–21, an inhibitor of FZD7, inhibits the growth of gastric adenomas and is currently being evaluated in preclinical trials for patients with gastrointestinal tumors." (PMID 38952556, 2024). "In addition, knockdown of FZD7 or treatment with vantictumab inhibited the growth of gastric adenomas." (PMID 38952556, 2024). "Both GC cells and mouse gastric adenomas show upregulation of c-Myc in an Fzd7-dependent manner." (PMID 32486243, 2020). "Also, FZD7 might be crucial for Wnt-driven gastric adenoma formation, most likely through the Wnt/β-catenin pathway." (PMID 33869179, 2021). "In the gastric adenomas of Cre+ gp130F/F Fzd7fl/fl mice, Fzd7-deleted cells were not repopulated but rather survived 20 days post-tamoxifen induction and are thus unable to respond to Wnt signaling, and subsequently failed to proliferate." (PMID 32486243, 2020).
intestinal cancer (3 papers, 2016 to 2025). "Physiologically, FZD7 is essential for the maintenance of the intestinal epithelium and exaggerated FZD7 signaling is associated with the development of intestinal cancers, but also other forms of cancer." (PMID 41392205, 2025). "As Lgr5+ stem cells are the cell of origin for intestinal cancer and also a marker of intestinal cancer stem cells, this data opens new avenues of research to determine the therapeutic benefit of inhibiting Fzd7 to specifically target these cells." (PMID 27196929, 2016). "Dysregulationof FZD7 and exaggerated WNT/β-catenin signaling isfrequently observed in intestinal cancers." (PMID 39670643, 2024).
osteosarcoma (3 papers, 2014 to 2022). A usually aggressive malignant bone-forming mesenchymal neoplasm, predominantly affecting adolescents and young adults. "In osteosarcoma, through the miR-93-3p/FZD7 axis, MIR4435-2HG can also up-regulate FZD7 and activate the Wnt/β-catenin signaling pathway, thereby promoting the proliferation, invasion, and migration of osteosarcoma cells." (PMID 35784328, 2022). "In osteosarcoma, the MIR4435-2HG/miR-93-3p axis can up-regulate FZD7 and promote tumor progression." (PMID 35784328, 2022).
acute lymphoblastic leukemia (2 papers, 2022 to 2025). Leukemia with an acute onset, characterized by the presence of lymphoblasts in the bone marrow and the peripheral blood. "FZD7 is expressed by the majority of acute lymphoblastic leukemia (ALL) cells." (PMID 40171220, 2025). "FZD7 and FZD8 are expressed in most acute lymphoblastic leukemia (ALL) cells, while FZD3, FZD4, and FZD9 are occasionally detected." (PMID 36452482, 2022).
basal cell carcinoma (2 papers, 2020 to 2023). A carcinoma involving the basal cells. "Indeed, the genes driving the basal cell carcinoma pathway are FZD9, FZD7, FZD2, DVL1, and AXIN1, all playing a role in the Wnt signaling pathway, which has already been linked to AD and PD." (PMID 33362460, 2020).
bladder cancer (2 papers, 2007 to 2022). "Similarly, transfection of bladder cancer cells with miRNA-27a mimic leads to the downregulation of P-gp, which appears to be related to the FZD7 (frizzled class receptor 7)/β-catenin pathway." (PMID 35205839, 2022).
breast tumor (2 papers, 2012 to 2023). "Together, these data suggest that FZD7+ cells are enriched in basal-like breast tumor models." (PMID 37943878, 2023). "As components of the Wnt signalling pathway such as FZD7 and FZD4 are disrupted in many cancer types including colon, renal, brain and breast tumours, it is believed they promote the ability of the tumour to proliferate and invade the surrounding tissue." (PMID 22536405, 2012).
chronic myeloid leukaemia (2 papers, 2019 to 2025). "FZD7 was closely connected to the signaling pathways for focal adhesion, chronic myeloid leukemia, and neurotrophin in a variety of distinct ways." (PMID 40171220, 2025).
diabetes (2 papers, 2017 to 2020). "Expression levels of ROR2, FZD7, VANGL2 and PRICKLE1 correlated with each other, and these correlations were statistically significant in subjects with and without diabetes, although in most cases they were much stronger in the group with diabetes." (PMID 29229927, 2017). "Specifically, VAT expression of ROR2, FZD7, VANGL2 and PRICKLE1 correlated with that of DSH1,2,3 and DIVERSIN/ANKRD6 in the diabetes group, but not in most cases in the group without diabetes." (PMID 29229927, 2017).
leukaemia (2 papers, 2008 to 2016). "Here, we also found an interaction between the bone marrow micrienviroment and leukemia cells partially mediated by FZD7." (PMID 26716419, 2016).
metastatic cancer (2 papers, 2014 to 2018). A carcinoma which has spread from the original site of growth to another anatomic site. "SIRT1 inhibition could possibly be considered a target for treatment of metastatic cancers where both FZD7 and SIRT1 are overexpressed." (PMID 24897117, 2014).
metastatic tumor (2 papers, 2017 to 2024). "IHC analysis in primary tumors from patients diagnosed with HGSOC (stage: 3 + 4, grade: 3) revealed increased Fzd7 and active-p-ILKSer246 levels compared to corresponding adjacent normal ovarian epithelium, both Fzd7 and p-ILKSer246 staining was greatest in metastatic tumors." (PMID 38822429, 2024).
nasopharyngeal carcinoma (2 papers, 2008 to 2016). A carcinoma arising from the nasopharyngeal epithelium. "Likewise, FZD7 is upregulated in nasopharyngeal carcinoma, and Wnt signalling is deregulated in head and neck cancer, but the importance of FZD7 has not been studied." (PMID 27196929, 2016).
Obesity (2 papers, 2019 to 2025). Accumulation of substantial excess body fat. "This might lead to an increase in FZD7 expression, activation of the Wnt/Fzd signaling, and thus attenuation of obesity." (PMID 31443156, 2019).